TNF (tumor necrosis factor)
Diseases named in the same sentence as TNF in open-access papers (continued):
Sharing a sentence is not in itself a finding about the gene and the disease.
cancer (continued). "Under both conditions, of direct or indirect interactions between the cancer cells and monocytic cells, elevated levels of stemness, EMT or both were frequently mediated by inflammatory factors such as TNFα, IL-6 and/or ELR+ CXC chemokines that will be particularly mentioned in more detail later on." (PMID 33585241, 2020). "TILs kill cancer cells by releasing cytokines, such as IFN-γ, IL-2, and TNF-α." (PMID 32964058, 2020). "Cholix-induced apoptosis was regulated by mitogen-activated protein kinase (MAPK) and protein kinase C (PKC) signaling pathways, which dramatically enhanced tumor necrosis factor-α (TNF-α) production in human liver, as well as the amount of epithelial-like HepG2 cancer cells." (PMID 33374361, 2020). "The results showed that there were 9 active components acting on key targets such as VEGFA, VWF, IL6, TNF, NFKB1, respectively, as well as regulating signaling pathways such as AGE-RAGE, FA, Toll-like receptor, PI3K/Akt, NF-κB, apoptosis and cancer signaling pathways." (PMID 33424592, 2020). "We started with trajectory reconstruction on the time-series datasets of an OVCA420 cancer cell line undergoing EMT induced by three different external signal (TGFB1, EGF, and TNF) and uncovered the existence of multiple ICSs displaying hybrid epithelial and mesenchymal features." (PMID 33488673, 2020). "Pivotal mediators of cancer-induced cachexia are the transcription factors STAT3 and NF-κB, which, in turn, are mainly activated by the circulating pro-inflammatory cytokines, such as IL6 and TNFα, respectively." (PMID 32824440, 2020). "It should be investigated in an intervention study, whether adopting a healthier lifestyle during and after cancer treatment results in lower levels of inflammation markers (IL6, TNFα), and ultimately less fatigue." (PMID 33317113, 2020). "In order to produce a new oncolytic adenovirus that replicates specifically in ARE-mRNA-stabilized cancer cells, we constructed an adenovirus including the ARE of the TNF-α and c-fos genes in the 3′-UTR of the E1A gene and designated them AdARET and AdAREF, respectively." (PMID 32403262, 2020). "Additionally, gene set enrichment analysis revealed enrichment of TNF-alpha and type-I IFN response genes among sensitive, and TGF-beta and fibronectin related genes in resistant cancer cells." (PMID 33237942, 2020). "Six months post-diagnosis, fatigue was assessed with the European Organization for Research and Treatment of Cancer quality of life questionnaire C30 (EORTC QLQ-C30), and in a subpopulation, the plasma levels of inflammation markers (IL6, IL8, TNFα, and hsCRP) were assessed." (PMID 33317113, 2020). "A combined treatment of TNF-α and DOX is a promising chemotherapeutic strategy to overcome cancer." (PMID 32225068, 2020). "More studies on TNF-α and other compounds with CS ability and their therapeutic effects on MDR cancer cells can lead to finding new targets and therapeutic procedures to overcome resistance in MDR cancer cells." (PMID 32742605, 2020). "Collectively, these results indicate that restoration of miR-203 and miR-200c expression in 16B/TNF cells reverses the TNFα-induced CSC properties, suggesting that chronic TNFα exposure promotes cancer stemness of HOK-16B cells through downregulation of miR-203 and miR-200c." (PMID 31911577, 2020). "However, the implements of TNF-α or TNFR1 therapeutic practices are unsatisfactory owing to the dual function and complexity of TNFR1-mediated signaling during cancer development 6-8." (PMID 32929358, 2020). "Flavonoids have been reported to induce apoptosis of human cancer cells, inhibit NF-κB and the IL-6/STAT3-mediated inflammatory signalling pathway, and also regulate levels of inflammatory cytokines such as IL-6, IL-1β, and TNF-α." (PMID 33082817, 2020).
cancer (continued). "We assessed four different cancer cell lines capable of undergoing an EMT (A549, lung; DU145, prostate; MCF7, breast; and OVCA420, ovarian) and exposed each to known EMT-inducing factors: TGFB1, EGF, and TNF." (PMID 32358524, 2020). "We found that AIM suppressed NF-κB activation induced by TNF-α in MCF-7 cells, and the upregulation of NF-κB-regulated genes (COX-2; MMP-2, MMP-9, and VEGF) involved in cancer cell proliferation (COX-2, C-myc, Cyclin-D1), and invasion, adhesion, and angiogenesis (MMP-2, MMP-9, ICAM-1, VEGF)." (PMID 32455624, 2020). "We selected lansoprazole due to some anti-tumoral advantages such as suppression of tumor necrosis factor α (TNFα), NF-kB activity, phosphorylation of ERK, decreased adhesion of cancer cells to the matrix, synergy with metronomic chemotherapy, and synergy with carbonic acid inhibitors." (PMID 33287221, 2020). "Although TNF is widely considered a pro-inflammatory/survival signaling cytokine, we show that TAK1 inhibition blocks traditional TNF inflammatory and survival signaling and induces apoptosis in TAK1 dependent cancer cell lines." (PMID 32523651, 2020). "Other signaling pathways contributing to PH pathology, including TGFβ-smad signaling, TNFα-NFkB signaling, IL661,62, and CD44-LOX signaling are known to induce Twist1 expression in cancer cells and may be involved in the mechanism." (PMID 32371931, 2020). "From the studies conducted so far, candidate phytochemicals could inhibit TNF-α signaling and activity through TNFR1 or could block TACE and thereby inhibit inflammation, apoptosis, degeneration, cancer, and immune disorders in the brain." (PMID 31991572, 2020). "In contrast, IFN-γ/TNF did not induce SA-β-gal in the RT2.CRISPR-Cdkn2a-cancer cells, and the cells restarted exponentially growing after IFN-γ/TNF withdrawal, showing that RT2.CRISPR-Cdkn2a-cancer cells were resistant to CIS." (PMID 32165639, 2020). "The cancer chronic condition caused a pressuring effect on TNF-α, leading to a lack of TNF-α and TNF-α inhibition." (PMID 33369455, 2020). "TNFα release by these CD16+ monocytes upregulates type 2 beta integrins (CD11a, CD11b), which facilitate the interaction between CD16+ monocytes and antibody-coated cancer cells." (PMID 32733461, 2020). "We explored whether Th1-cytokines, IFNγ and, TNF-α, can modulate the KYN downstream metabolites such as 3-HK, 3HAA, and AA in cancer cells." (PMID 32117720, 2020). "Regarding TNF-α effects on cell proliferation, it should not be overlooked that TNF-α has its own anti-cancer effect, so some cancer cell such as MCF-7 cells are susceptible to TNF-α treatment." (PMID 33233701, 2020). "Both TNF-α and IFN-γ are known to contribute to cancer growth inhibition." (PMID 33255436, 2020). "Tumor necrosis factor (TNF) superfamily ligands show diverse biological functions, such as the induction of apoptotic cell death or cell survival and proliferation, making them excellent therapeutic targets for cancer and autoimmunity." (PMID 32245106, 2020). "Under healthy physiological condition, adiponectin inhibits IL-6 and TNF and seems to have a functional interplay with IGF-1 that may be impaired in cancer patients." (PMID 32230855, 2020). "In sum, AP rapidly stimulates the degranulation of cytotoxic granules and the production of the anti-cancer cytokines IFNγ and TNFα in Vγ9Vδ2 T cells but not within other T cells." (PMID 32604868, 2020). "It is plausible that in certain contexts or cancer cells, FADD may serve as an adaptor protein that links TNFα signaling to the pro-survival NFκB pathway." (PMID 32194778, 2020). "A total of 155 nodes, including 20 putative targets of HZJD decoction, were selected as core hubs based on topological importance and were closely associated with the regulation of cell proliferation, apoptotic process, and cancer-related pathways (AKT1, TNF, VEGFA, and EGFR) in CAG." (PMID 33354218, 2020).
cancer (continued). "The inflammatory cytokines such as IL-1, IL-6, TNF- α, and TGF-β could induce cancer cells proliferation and tumoral invasion through activation of NF-κB." (PMID 32458652, 2020). "Another study showed a significant association between cholinesterase activities including BChE with IL-6 and TNF-α but not with CRP in frail elderly patients without cancer." (PMID 32375339, 2020). "Moreover, it has been recently demonstrated that tumors from cachectic patients have higher TNF-α and monocyte chemoattractant protein 2 (CCL2) gene expression, along with higher CCL3 protein expression than those of weight stable cancer patients." (PMID 33604297, 2020). "These sub-networks showed the interactions between paracrine factors and their receptors including TNF-TNFR, NRG1-EGFR (ERBB), and WNT-FZD further indicated that paracrine factors TNF, NRG1, and WNT from infiltrated dendritic cells were involved in cancer pain." (PMID 32434423, 2020). "Leptin increases the expression of anti-apoptotic proteins, inflammatory markers (tumor necrosis factor, TNF-α, interleukin IL-6) and angiogenic factors (vascular endothelial growth factor, VEGF), all processes involved in cancer cell survival, proliferation and migration." (PMID 32854444, 2020). "The monoclonal antibodies affected cytokine secretion, including MCP-1, IL-6, and TNF-a, but the effect on cancer cell viability or survival have not been investigated." (PMID 33238461, 2020). "Moreover, after receiving cancer treatment radioactivity in lung cells diminished and cancer promoting factors declined (VEGFR2, ICAM-1, bFGF, KC, TNF-α, IL-6, IL-12, IL-10 and IL-13) showing a diminution of metastatic competency of the exosomes." (PMID 32570802, 2020). "Both TNF-α and IL6 are known to have complex effects and dual roles in cancer." (PMID 33123499, 2020). "However, the potential therapeutic, or even deleterious, effects of targeting TNF in other inflammatory conditions, such as cardiovascular disease (CVD) and cancer remains equivocal." (PMID 32805626, 2020). "Surprisingly, the main cytokines, IL-6 and TNF-α, usually assayed in cancer models, presented no changes in our conditions." (PMID 32472095, 2020). "Cluster II was enriched for IL-17 signaling pathway, TNF signaling pathway, and cytokine–cytokine receptor interaction, and Cluster III was related to MAPK signaling pathway, PI3K-Akt signaling pathway, and MicroRNAs in cancer." (PMID 33043974, 2020). "IL-6, TNF-a and PGE2 produced by primary oral keratinocytes and carcinoma cells may induce oral mucosal inflammation." (PMID 31969157, 2020). "In addition, studies have reported that 11 cancer markers in overweight patients are significantly higher than those in normal weight patients, including ANG-2, sFASL, HB-EGF, IL-8, PLGF, TGF-α, TNF-α, uPA, VEGF-A, VEGF-C, and VEGF-D." (PMID 31440472, 2019). "Moreover, KEGG pathway analysis indicated that the TNF signaling pathway, MAPK signaling pathway, cytokine-cytokine receptor interaction, and pathways in cancer were the most significantly enriched pathways." (PMID 31354385, 2019). "Fibroblast-fibroblast connections can physically prevent cancer progression by three-dimensional networking and thus affecting ECM stability as well as by paracrine signaling, e.g., secretion of tumor necrosis factor α (TNFα) and IL-6." (PMID 31475157, 2019). "Thus, we examined the functional activity of expanded NK cells under specific condition by evaluation of CD107a expression, secretion of TNF-α and IFN-γ and the expression level of Perforin and Granzyme against target cancer cells." (PMID 31870124, 2019).
cancer (continued). "Additionally, the most significant signaling pathways of upregulated genes included the TNF signaling pathway (KEGG:rno04668), PI3K-Akt signaling pathway (KEGG:rno04151), and pathways in cancer (KEGG:rno05200)." (PMID 31379949, 2019). "Reduction of pro-inflammatory cytokines (e.g., IL-6, TNF-α, and IFN-ɣ) levels were observed when using the triple combination, which indicated that the synergistic drug combination was able to significantly control cancer progression." (PMID 31635311, 2019). "Cancer process is responsible for the activation of the NF-κB pathways leading to the over-expression of pro-inflammatory factors, including COX-2, iNOS, cytokines, TNF-α." (PMID 31331376, 2019). "Surprisingly, a majority of the TNF-α mRNA expressing cells were found to be cancer cells and not inflammatory cells." (PMID 30999696, 2019). "We previously reported that tRXRα could promote TNFα activation of the PI3K/AKT signaling pathway, another important pathway critical for cancer cell proliferation and survival." (PMID 30931933, 2019). "Indeed Tumor Necrosis Factor-alpha (TNF-α) and its stimulating role in cancer has been well studied, but the role of its closest homologue TNF-β (alias Lymphotoxin-α) remains to be elucidated." (PMID 30917533, 2019). "Consistent with our findings, other studies also found no role for the same genes we tested in studies where populations enrolled were not enriched for positive cancer family history (for example, TNF-a or MDM2)." (PMID 30601841, 2019). "Furthermore, nine cancer biomarkers: MIF, TNFα, sFasL, TRAIL, FGF2, SCF, prolactin and OPN, were negatively correlated to Lactobacillus abundance and positively correlated to levels of vaginal pH." (PMID 31089160, 2019). "We found that miR-21 also co-localizes in some, but not all, of these cancer cells, suggesting that miR-21 is not co-regulated with TNF-α mRNA, and that the presence of TNF-α mRNA does not lead to suppression of miR-21 expression." (PMID 30999696, 2019). "We tested if cancer cells produce TNF-α, by ELISA of MDA-MB-231 and MDA-MB-468 CM, but did not detect significant levels." (PMID 30930117, 2019). "Inflammatory mediators such as tumor necrosis factor-alpha (TNF-α), Interleukin-6 (IL-6), Interleukin-10 (IL-10) and transforming growth factor-beta (TGF-β) play important roles in tumorigenesis and the development of cancer in different entities." (PMID 31077235, 2019). "Furthermore, a subset of cancer biomarkers (CYFRA 21-1, TNFα, TRAIL, leptin and sFasL) strongly discriminated the high and low diversity/inflammation cluster groups." (PMID 31089160, 2019). "The impact anti-TNF antibodies have on anti-cancer immune responses in these settings are not known." (PMID 31417576, 2019). "The mechanisms controlling cancer immune response are somehow conserved also in flies as studies in Drosophila have shown that infiltration of macrophages (called hemocytes) in cancer cells requires the activation of the JAK-STAT, JNK, TNF-α, and Toll/Imd/TLR signaling pathways." (PMID 30881374, 2019). "Enhanced EMT properties in cancer cells (A549, MCF7, and HepG2) by the TGF-β, IFN-γ, and TNF-α may affect differentiation and death of natural killer (NK), T, and B cells." (PMID 31766574, 2019). "The cross-talk between adipocytes and cancer cells is mediated by cytokines (specifically IL-1, IL-6 and TNF-α), adipokines, including APN and other molecules, released by adipose tissue, able to control proliferation and invasion of different cancer cell types." (PMID 30781341, 2019). "Tumor necrosis factor (TNF)-related apoptosis-inducing ligand (TRAIL)-mediated signaling has emerged as one of the most highly and extensively studied signal transduction cascade that induces apoptosis in cancer cells." (PMID 31022877, 2019).
cancer (continued). "Seminal studies have shed light on T-cell exhaustion in human cancers, where CD8 T cells lose proliferative capacity, the ability to produce tumor necrosis factor (TNFα), interleukin-2, and interferon-γ (IFNγ), and upregulation of inhibitory checkpoint receptors, such as PD-1 and CTLA-49–11." (PMID 31804466, 2019). "Our study showed that no apparent changes of plasma TNF-α in cancer cachexia patients were observed in both genders." (PMID 31788012, 2019). "The use of recombinant TNF has been previously proposed for cancer therapy, but significant toxicities and lack of efficacy prevented its clinical success for systemic application." (PMID 31803362, 2019). "Moreover, molecules such as Histamine, Tumor Necrosis Factor alpha (TNF-α), Lipopolysaccharide (LPS), are known to promote endothelial hyperpermeability and adhesion molecule exposure, suggesting a potent role over cancer metastasis." (PMID 31382462, 2019). "Interestingly, we found that TNFα induced E-cadherin cleavage and extracellular shedding in DU145 cancer cells, which was dependent on the upregulation of endogenous RHBDL2, as demonstrated by the gene knock-down experiments." (PMID 31783481, 2019). "We evaluated the concentration of ANG-2, FGF-2, HGF, IL-8, PDGF-BB, TIMP-1, TIMP-2, TNF-α, and VEGF that are the major cytokines involved in angiogenesis in MM and other cancers and, as previously demonstrated in MM patients, directly correlate with disease activity and increase with progression." (PMID 30626425, 2019). "In agreement with our results, autophagy was inhibited in TNFα-treated Caco-2 cells, and TNFα acted as an activator of mTOR via IκΒ-kinases involving or not AKT in different cancer cell models." (PMID 30546074, 2019). "Interestingly, LIGHT and TNF-α treatment induced HIF levels to a similar degree, suggesting that both cytokines can activate HIF mediated responses in cancer cells." (PMID 30096845, 2018). "Since TNFα is the major cytokine responsible for M1-type macrophage-induced EMT, we examined whether TNFα-primed cancer cells harbored IL-35 receptor to receive signals at metastatic sites." (PMID 30218063, 2018). "On the other hand, TNF-α, Ras and TGF-β may work as upstream regulatory signals of ΔNp63 that stimulate cancer progression." (PMID 30018747, 2018). "Even in the early stages of cancer progression, tumors produce various factors including cytokines, chemokines, growth factors, and transcription factors; this includes IL-6, CRP, and tumor necrosis factor (TNF)-α, to name a few." (PMID 30042700, 2018). "Expression analysis also indicated involvement of extrinsic pathway of apoptosis in PN-treated cells as increased levels of TRAIL R1/D4, TRAIL R2/D5, TNFα, Fas and FADD were observed in some of the PN-treated cancer cells at 48 h in comparison to vehicle treated cells." (PMID 29420562, 2018). "Indeed, the anti-inflammatory effects of PS to lower mRNA levels of IL-1β, TNFα, iNOS, and COX-2 in HT-29 colon cancer cells have been identified to impact therapeutic strategies against cancer progression." (PMID 29346311, 2018). "The most important vaccine with anti-cancer activities is ADXS 11-001 (or ADXS-HPV, formerly known as Lovaxin-C), a therapeutic Listeria-based vaccine targeting an HPV E7 antigen and resulting a TNF-alpha (TNF-α) response and IL-2 production by DCs." (PMID 30483247, 2018). "Some common pro-inflammatory cytokines used to induce proliferation and invasion of cancer cells include lipopolysaccharide (LPS), epidermal growth factor (EGF), tumor necrosis factor α (TNFα), interleukin β (IL-β), interleukin 6 (IL-6) and prostaglandin E2 (PGE2)." (PMID 30603045, 2018).